INS (insulin)
Diseases named in the same sentence as INS in open-access papers (continued):
Sharing a sentence is not in itself a finding about the gene and the disease.
Hyperglycemia (continued). "In our study, we found that the weight gain as well as the HOMA-IR were significantly higher in the 1-hour GIGT hyperglycemia than in the 2-hourand 3-hour subgroups, showing that a 1-hour glucose abnormality in GIGT patients was associated with higher insulin resistant severity." (PMID 25674108, 2014). "In addition, insulin is the most studied hormone in the maternal and fetal organism in an attempt to understand the repercussions of hyperglycemia." (PMID 24977161, 2014). "In addition, insulin secretion from pancreatic cells and improvement of glucose metabolism can reduce hyperglycemia." (PMID 25053966, 2014). "Here, we characterize and quantify the secretome and glycome of primary human adipocytes during insulin responsive and insulin resistant conditions generated by the classical method of hyperglycemia and hyperinsulinemia or by the pharmacological manipulation of O-GlcNAc levels." (PMID 24948903, 2014). "At present it is unknown whether activation of this alternative intracellular pathway of the IGF-IR occurs during hyperglycemia in vivo and whether it is stronger in patients treated with (some) insulin analogs than in patients treated with human insulin." (PMID 24904529, 2014). "The link between cognitive impairment and poor metabolic control may be largely mediated by the structural and functional brain changes that occur in the presence of chronic insulin dysregulation and hyperglycemia." (PMID 25071557, 2014). "Indeed, many CF patients suffer from postprandial hyperglycemia although they have normal fasting plasma glucose levels indicating that the beta-cells fail to respond upon increased insulin demand." (PMID 24885604, 2014). "This suggests that insulin was unable to restrain the breakdown of liver glycogen to the same extent in the Chow and both ND groups; however the liver still retained the metabolic memory to augment glucose oxidation in response to hyperglycemia." (PMID 24465939, 2014). "Moreover, many CF patients, also those without CFRD, have normal fasting plasma glucose levels, but suffer from postprandial hyperglycemia indicating that the beta-cells fail to respond upon increased insulin demand." (PMID 24885604, 2014). "Nevertheless, this study concluded that SIR could be a biological response to hyperglycemia and we demonstrated that it is a response to high insulin levels." (PMID 24995000, 2014). "In addition PRAS40 treatment improves hepatic insulin sensitivity and reduces systemic hyperglycaemia in obese mice." (PMID 24408966, 2014). "However, normoglycemia persisted in VTN (BG = 81 ± 5 mg/dL) and CN, but 10 days after STZ injection, severe hyperglycemia (BG = 395 ± 9 mg/dL) with low level of insulin (0.75 ± 0.01 ng/dL) was observed in diabetic rats." (PMID 24842144, 2014). "We have also confirmed hyperglycemia and hyperinsulinemia in the obese Zucker model comparative to lean controls, with plasma glucose and insulin concentrations of 271.2 ± 36.2 mg/dL versus 110.4 ± 18.2 mg/dL (p < 0.005) and 11.8 ± 0.3 μUnits/mL versus 3.8 ± 0.7 μUnits/mL (p < 0.001), respectively." (PMID 25547587, 2014). "Repaglinide is an insulin secretagogue agent with a more rapid anti-hyperglycemic action and a shorter duration than SUs, and therefore provides better control of postprandial hyperglycemia." (PMID 24843385, 2014). "Type I diabetes occurs when the pancreas fails to produce enough insulin and the insufficient production of insulin causes hyperglycemia." (PMID 24696697, 2014). "We hypothesized that the increased ERα mRNA expression in islets exposed to hyperglycemia could be due to the stimulatory effect of high glucose or to the impact of elevated insulin on the IR in the islets." (PMID 24498408, 2014).
Hyperglycemia (continued). "Hyperinsulinemia has also been associated with diminished Sex Hormone-Binding Globulin (SHBG) levels, although insulin appears to be unable to directly inhibit shbg expression; instead, this effect depends on hyperglycemia-mediated Hepatocyte Nuclear Factor 4-α downregulation." (PMID 25763406, 2014). "Certainly, these data suggest that all diabetic patients with a head injury would benefit from an insulin sliding scale with scope for recommendation that all patients who have a head injury and deranged blood glucose should have aggressive correction of hyperglycemia with insulin." (PMID 25026864, 2014). "In addition, there are limited local and global data on the level of glycemic control achieved in T2DM patients with severe or acute hyperglycemia based on the type of insulin regimen used." (PMID 25181406, 2014). "The issue of insulin therapy and lowering hyperglycemia has been greatly discussed but to the best of our knowledge, there is no previous study focused on the immediate effects of insulin on lung physiology and the transcription of surfactant proteins performed on actual patients." (PMID 25278226, 2014). "The excessive fat in a mother may decrease insulin sensitivity in a fetus and lead to hyperglycemia that induces pancreatic β-cell proliferation." (PMID 25050345, 2014). "It has been suggested that the therapeutic effect of insulin could be related to tighter glycemic control, since it has been suggested that hyperglycemia stimulates inflammatory pathways in immune cells." (PMID 25101057, 2014). "Herein, we confirm hyperinsulinaemia, hyperglycaemia, reduced insulin sensitivity and skeletal muscle atrophy in the T2D obese Zucker rat, but importantly determine that this atrophy is not caused by sarcolemmal damage, elevated lipid peroxidation and degradative calpain activity." (PMID 25547587, 2014). "The recurrence of hyperglycemia was observed upon removal of the insulin implants in these mice." (PMID 24743240, 2014). "Thiazolidinediones (TZDs) are true insulin-sensitizers and can improve hyperglycemia, but these agents tend to increase adiposity, have minimal effects on hyperlipidemia, cause fluid retention, and may increase cardiovascular risk." (PMID 26237474, 2014). "In addition to insulin-mediated effects, hyperglycemia is thought to provide energy for malignant cell proliferation, which because of their dependence on aerobic glycolysis (Warburg effect), favors cancer cell growth." (PMID 24722238, 2014). "However, in many instances compensatory insulin secretion eventually diminishes as a result of beta cell dysfunction leading to uncontrolled hyperglycemia." (PMID 24533136, 2014). "However, impaired insulin secretion due to beta cell failure seems to be the key defect leading to the deterioration of hyperglycemia after a pregnancy affected by GDM." (PMID 25174260, 2014). "However, to the best of our knowledge, effect of myriocin on lipid metabolism in case of severe hyperglycemia induced by streptozotocin (chemical compound toxic to the insulin-producing pancreatic β-cells) remains unexplained." (PMID 24701589, 2014). "Studies have suggested that hyperglycemia in ICU patients primarily arises from increased insulin resistance rather than loss of insulin secretion." (PMID 24886999, 2014). "Although the difference in the time action profiles of glargine and NPH has been well established, there are no studies examining whether patients with fasting as compared to postprandial type hyperglycemia benefit more from NPH than glargine insulin." (PMID 23880900, 2014). "Together these results suggest that hyperglycemia inhibits complement opsonization of S. aureus early in infection and that insulin rescue may improve C4-mediated opsonization." (PMID 25610878, 2014). "Tofogliflozin may have the potential to prevent or improve not only hyperglycemia but also insulin sensitivity by suppressing TG accumulation and inflammation in the adipose tissue and liver." (PMID 25000147, 2014).
Hyperglycemia (continued). "• Aerosolized insulin shows effects beyond mitigating hyperglycemia." (PMID 23622115, 2013). "However, in captivity, under conditions of restrained physical activity and of high energy diet (HE) feeding, P. obesus rapidly develop hyperglycemia, hyperinsulinemia and marked depletion of pancreatic insulin content." (PMID 24009765, 2013). "Most are retrospective with a very large GC dose range, different DM diagnostic criteria, comorbid conditions that affect insulin sensitivity, and with no description of the course of hyperglycemia." (PMID 23557386, 2013). "But diazepam may alter insulin secretion and insulin sensitivity after a single administration in healthy volunteers, and diazepam-induced hyperglycemia, might be related to changes in serum chromium levels." (PMID 24134697, 2013). "Finally, the maturity-onset nature of hyperglycemia coupled with the less extreme plasma concentrations of insulin and leptin makes the polygenic models much more reflective of the most common forms of human T2D." (PMID 23671854, 2013). "The results suggest that insulin attenuates inflammatory responses in the lungs augmented by hyperglycemia in acute lung injury and the insulin's efficacy may be better when administered by aerosol." (PMID 23622115, 2013). "In states of increased insulin demand such as hyperglycemia, beta cells compensate to restore glucose homeostasis (maintain normoglycemia) via beta cell hypertrophy, and hyperplasia (to collectively increase beta cell mass) also increasing insulin biosynthesis." (PMID 23542897, 2013). "It is characterized by hyperglycemia due to shortage in the secretion and/or actions of insulin." (PMID 23384060, 2013). "Several approaches have been recommended to reduce hyperglycemia, including increasing pancreatic insulin release by sulfonylureas, decreasing hepatic glucose production by metformin, enhancing insulin action by thiazolidinediones, and suppressing gut glucose absorption by α-glucosidase." (PMID 23690865, 2013). "Although generation of ATP requires by far more glucose than oxidative phosphorylation (feature which is used in PET imagining), malignant cells are already adapted to highly effective glucose uptake independently of insulin signaling, so that additional favorable effect of hyperglycemia is unclear." (PMID 23476808, 2013). "Insulin has been used to treat acute or stress hyperglycemia clinically." (PMID 24371503, 2013). "Additional mechanisms contributing to hyperglycemia including alterations in glucose delivery due to tissue perfusion, increases in counter-regulatory hormones, changes in lipid profiles, and impaired insulin signaling remain to be explored in CLP mice receiving glucose support." (PMID 23826335, 2013). "However, when the metabolic demands exceed the compensatory capacity of the increased beta cell mass and insulin secretion, hyperglycaemia and T2D will develop." (PMID 24324833, 2013). "Metabolic analyses reveal that deletion of the Pdk4 gene had better improvement in hyperglycemia and glucose tolerance than knockout of the Pdk2 gene whereas the Pdk2 gene deletion showed better insulin tolerance as compared to the Pdk4 gene inactivation on the Irs1/2 knockout genetic background." (PMID 23940800, 2013). "In the present studies, 9 to 12 hours of hyperglycemia induced by insulin discontinuation increased left ventricular contractile function in T2D patients irrespective of whether LVEF was preserved or reduced." (PMID 23308171, 2013). "Moreover, insulin treatment alleviated hyperglycemia, markedly activated Akt and AMPK and showed a significant increase in GLUT4 translocation and subsequent glucose uptake in ischemia-reperfused STZ hearts with or without IPC." (PMID 23922853, 2013).
Hyperglycemia (continued). "Conversely, if the foetus does not inherit the mutation, foetal hyperinsulinemia with resultant increased foetal growth, as a consequence of ambient hyperglycaemia in utero may occur, unless maternal blood glucose is reduced by insulin therapy." (PMID 23766565, 2013). "When the animals exhibit severe bluntness of glucose-stimulated insulin secretion and low serum levels of insulin in association with hyperglycemia, it is not possible to quantify SI from a regular IVGTT." (PMID 23762879, 2013). "Chronic exposure hyperglycemia, leading to oxidative stress and inflammation, may induce changes in the regulation of gene expression that converge on impaired insulin secretion and increased apoptosis." (PMID 23542897, 2013). "The delay in the onset and robust control of hyperglycemia observed in this study appear to be mediated by the combined effects of enhanced phasic insulin secretion, improvement in glucose sensitivity of beta cells, increased insulin content and reduction in beta cell apoptosis." (PMID 23692921, 2013). "GLP-1 is effective in restoring first-phase insulin response and lowering hyperglycemia in T2DM." (PMID 24191197, 2013). "Alternatively, the clamp may be used to estimate insulin secretory responses to standardized raised glucose levels by targeting hyperglycemia values, like 8.3 or 11.1 mmol/L." (PMID 23762879, 2013). "Any defect in insulin synthesis/secretion or action, or both, may result in hyperglycemia, a major pathological feature of type 2 diabetes (T2D)." (PMID 23573144, 2013). "In fact, tau modification can be induced by insulin dysfunction and hyperglycemia, which may contribute to the increased incidence of Alzheimer's disease in diabetic patients." (PMID 23776493, 2013). "It is known that insulin-producing cells derived from human embryonic stem cells or human pancreatic islet progenitor cells could correct hyperglycemia in diabetic mice." (PMID 24268157, 2013). "Hyperglycemia occurs only in those individuals able to secrete sufficient compensatory insulin." (PMID 24892324, 2013). "Due to hyperglycemia, her insulin was changed to insulin 70/30, 10 units twice a day." (PMID 26425568, 2013). "For noncritical ill diabetic inpatients, they suggested the use of specific insulin regimens with combined basal and short-acting insulin and appropriate bedside glucose monitoring, avoiding the use of sliding-scale insulin (fast or rapid-acting insulin in response to hyperglycemia) alone." (PMID 24499564, 2013). "The insulin dosage was reduced by approximately 70% (T2D-HF: 60±31 IE vs. 20±11 IE, p<0.001; T2D-nonHF: 61±14 IE vs. 14±11 IE, p<0.001) in each study group during hyperglycemia 24 hours before the investigations as compared with normoglycemia." (PMID 23308171, 2013). "This may be due to the timing of insulin treatment after hyperglycemia onset considering insulin mini-pumps were implanted at E13.5, seven days after STZ administration." (PMID 23516451, 2013). "Additional symptoms that may be present are cold diuresis, mental confusion, hepatic dysfunction, and hyperglycemia due to the decrease in glucose uptake by cells, a decrease in insulin secretion, and impaired tissue sensitivity to insulin." (PMID 24363826, 2013). "However, the present studies were designed to evaluate on the effect of overall metabolic derangement occurring during hyperglycemia due to insulin discontinuation." (PMID 23308171, 2013). "Additionally, it must be noted that control of hyperglycemia is more difficult during the active phase of tuberculosis and many patients require insulin for control of hyperglycemia." (PMID 24360398, 2013). "It should be remembered that hyperglycemia induced by high dose glucose infusion may differ from hyperglycemia due to insulin resistance frequently seen in critically ill patients." (PMID 23622115, 2013).
Hyperglycemia (continued). "This can have lowered the threshold to delayed preconditioning since insulin has a preconditioning effect, and hyperglycemia and hypercholesterolemia are key player in the induction of atypical isoforms of protein-kinase C, which is crucial in the delayed preconditioning pathway." (PMID 23432808, 2013). "Our findings may be explained by the Pedersen hypothesis, which suggests that maternal hyperglycemia (even within the normal range) increases fetal insulin levels, leading to accelerated fetal growth." (PMID 24151621, 2013). "It has been suggested that cytokines, commonly increased during febrile diseases like interleukin-1 or tumor necrosis factor, may inhibit insulin release and increase the secretion of cortisol, further explaining hyperglycemia." (PMID 23741481, 2013). "Hyperglycemia can be handed initially with oral synthetic agent and insulin therapy." (PMID 24151502, 2013). "In addition, hyperglycemia increases intracellular calcium levels in cardiomyocytes independently of insulin." (PMID 23308171, 2013). "For people who do initiate insulin therapy during a hospital stay as part of their regular hyperglycemia treatment, prescriptions will be transferred to the community pharmacy once they are discharged, thereby introducing only a minor distortion in insulin therapy start date." (PMID 24223860, 2013). "As such, low levels of circulating insulin in our pigs potentially mean low levels of hypothalamic insulin signaling; this may contribute to fasting hyperglycemia and dysregulated energy intake." (PMID 23991090, 2013). "Diet induced hyperglycemia while insulin and leptin levels remained unchanged." (PMID 23587409, 2013). "Indeed, an emerging body of evidence suggests that insulin suppresses the inflammatory process, not only through preventing hyperglycemia but also by modulating key inflammatory molecules." (PMID 24349194, 2013). "Above this level, the increase in MGU is small; and we therefore hypothesize that the combination of short-term hyperglycemia and the presence of circulating insulin of app." (PMID 23308171, 2013). "However, DPP-IV inhibitors as sitagliptin, through plasma GLP-1 stabilization and insulin control of hyperglycemia/lipidemia, reduced the cardiac pro-apoptotic/necrotic, hypertrophic and fibrotic expression in a similar way to metformin." (PMID 24302978, 2013). "It has been reported that in the progression of ZDF rat, the decrease of beta cell glucose transporter 2 (GLUT-2) membrane receptors and the concomitant loss of muscle glucose transporter 4 (GLUT-4) transporters are responsible for the impaired insulin secretion and subsequent hyperglycemia." (PMID 23671868, 2013). "Whether hyperglycemia induced by insulin discontinuation affects the function and performance of other organs, i.e. the lungs or muscles, and thereby improves walking distance and thus causes the present difference cannot be excluded." (PMID 23308171, 2013). "In addition, they exhibited phenotypes typical of metabolic syndrome and T2DM patients including hyperglycemia, hypertrehalosemia, peripheral resistance to exogenous insulin, and accumulation of triglyceride." (PMID 23326243, 2013). "Hyperglycemia may be exacerbated by the inability of hypotrophic and hypoplastic beta cells to synthesize and secrete sufficient insulin which consequently results in hypoinsulinemia." (PMID 23542897, 2013). "Neonatal hyperglycemia in DEND can be managed with insulin or sulfonylureas, but the latter is capable of bypassing the defective regulation of KATP channels and may have better efficacy for the neurological phenotype." (PMID 23762547, 2013). "To date, it has not been determined whether FGF21 based therapy, often deemed to correct hyperglycemia via an insulin sensitization mechanism, remains efficacious with regard to glucose endpoints in the context of low insulin levels." (PMID 23823755, 2013).